EPO (erythropoietin)
Diseases named in the same sentence as EPO in open-access papers (continued):
Sharing a sentence is not in itself a finding about the gene and the disease.
anemia (continued). "The prevalence of HCV is less prevalent in developed countries due to socioeconomic factors, better infection control measures, use of erythropoietin instead of blood transfusion to treat anemia." (PMID 25883732, 2014). "Knockout of EPO (EPO−/−) or EPO receptor (EpoR−/−) in mice results in embryonic death due to severe anemia." (PMID 24918289, 2014). "The levels of erythropoietin in younger children (<3 years) was significantly higher than in older children with a similar degree of malaria anaemia (Hb levels) (p < 0.005)." (PMID 25138388, 2014). "Erythropoietin (EPO) is a secreted glycoprotein produced primarily by the kidney and is used clinically to treat anemia." (PMID 24587228, 2014). "Recombinant human erythropoietin (RHuEPO) such as Epo alfa has proven efficacy in treating anemia in CKD patients." (PMID 24448756, 2014). "The current therapeutic use of rHuEPO to correct anemia in CKD patients has been associated with some cases of PRCA, due to the development of cross-reactive anti-EPO antibodies." (PMID 25580431, 2014). "In inflammatory bowel disease with anemia refractory to treatment with iron and vitamins, EPO administration in combination with oral iron improved anemia." (PMID 24918289, 2014). "Normal physiological compensation for anaemia is an increase in erythropoietin (EPO) from renal interstitial fibroblasts and hepatic perisinusoidal cells." (PMID 25265971, 2014). "Benefits of erythropoietin in adult treatment of chemotherapy-induced anemia were first demonstrated by Miller." (PMID 25598955, 2014). "Recombinant human EPO is approved for treatment of anemia resulting from chronic kidney failure, chemotherapy and antiviral treatment for Human Immunodeficiency Virus (HIV), and to reduce blood transfusions associated with selected major surgeries." (PMID 24918289, 2014). "In the case of CI-associated pathology, severe anemia as well as loss in bone marrow cellularity triggers stress erythropoiesis, which requires BMP4 and the formation of stress BFU-E driven by EPO stimulation." (PMID 24587369, 2014). "A prospective cohort study of patients in a randomized controlled clinical trial of correction of anemia with erythropoietin." (PMID 26038709, 2014). "Liver Atoh8 levels were reduced in mice under conditions associated with increased erythropoietic activity such as hypoxia, haemolytic anaemia, hypotransferrinaemia and erythropoietin treatment and increased by inhibitors of erythropoiesis." (PMID 24236640, 2014). "Further, kidney transplant candidates are frequently administered EPO injections for the treatment of anemia; hence, the pretransplant HbA1c level should be cautiously interpreted." (PMID 25386190, 2014). "Anemia is a common finding among patients who undergo HD which is usually corrected by human recombinant erythropoietin (EPO)." (PMID 24734095, 2014). "HIF-PH inhibitors provide a novel therapeutic approach to the treatment of anemia that is based on mimicking the hypoxia-driven expression of endogenous EPO in the kidney." (PMID 25392999, 2014). "The cause of iron overload in TI is likely to be due to a combination of ineffective erythropoiesis, anemia, and hypoxia leading to a compensatory increase in erythropoietin and a decrease in serum hepcidin." (PMID 24719849, 2014). "We aimed to investigate the potential benefits of omega-3 fatty acids as adjunct to IV iron and EPO treatment in correction of anemia in maintenance HD patients." (PMID 24397938, 2014). "Some studies showed that CAN can reduce the renal release of erythropoietin probably by renal denervation, leading to the development of anemia." (PMID 25505446, 2014). "Correction of anemia (and also supplementation of erythropoietin) was noted to decrease the effects of retinopathy with structural improvement, possibly through improved oxygenation of the macula." (PMID 24716846, 2014).
anemia (continued). "By loss of tissues, around the kidney tubules and its failure, amount of erythropoietin production reduced and anemia occurs." (PMID 25340147, 2013). "The role of VA in the recovery of nutritional anemia is possibly related to its modulation in the later stages of erythropoiesis, erythropoietin synthesis, and transcription of many hepatic genes." (PMID 24212089, 2013). "In a recent study, knockdown of hypoxia inducible factor (HIF)-2α in mice was shown to result in normocytic anemia despite unaltered erythropoietin levels." (PMID 23383068, 2013). "The most commonly observed adverse events (AEs) in the phase III trials were dose-dependent anemia and thrombocytopenia, which were anticipated as thrombopoietin and erythropoietin signal through JAK2." (PMID 24283202, 2013). "In this review, we compared the effects of erythropoietin and anemia correction on kidney function investigated in various studies." (PMID 25340147, 2013). "Vitamin D supplementation has long been known to improve anemia and reduce the need for erythropoietin in dialysis patients." (PMID 24015265, 2013). "Then, iron repletion is important, as even patients with suboptimal erythropoietin levels can correct anemia with adequate iron." (PMID 24151517, 2013). "Anaemia is a common haematologic side effect of dose-dense multi-cycle cytotoxic polychemotherapy requiring erythrocyte transfusions or erythropoietin (EPO) administration." (PMID 23755260, 2013). "Severe complications of end stage renal disease include anemia, which is at least in part the result of restricted renal erythropoietin release and subsequent impairment of erythropoiesis." (PMID 24188099, 2013). "Deleterious effects of anemia on stroke outcome have been described in patients, hence, previous studies also have shown that EPO mediated effects on memory function are independent from its effects on the erythropoietic system." (PMID 23497299, 2013). "Consistent with our data, previous study showed that the vitamin C supplementation improves the responsiveness to EPO in hemodialysis patients with refractory anemia and hyperferritinemia." (PMID 24228847, 2013). "It seems that the treatment of anemia by recombinant human erythropoietin in chronic kidney disease, when it accompanied by control of metabolic complications, can improve anemia but has not any effect on reduction of renal function rate." (PMID 25340147, 2013). "It was shown that decrease in EPO response to low hemoglobin concentrations contributes to anemia development in the elderly." (PMID 24453794, 2013). "Erythropoietin (EPO) provides an alternative to transfusion for increasing red blood cell mass and treating anemia in cancer patients." (PMID 24004818, 2013). "Erythropoietin is seldom used in the management of PTA, but for patients with poor graft function and moderate to severe anemia, erythropoietin is most likely the only efficacious medication available." (PMID 24237955, 2013). "Different notable evidences imply some benefits of erythropoietin other than the improvement of anemia such as the pleiotropic effects on the cardiovascular system and on the kidney." (PMID 25340134, 2013). "As hypoxia is one of the stimulators of VEGF, the correction of anaemia (or anaemia-induced hypoxia) with EPO would counteract the pro-angiogenic actions of VEGF and reverse IL-2 resistance." (PMID 23305401, 2013). "Recombinant human EPO (rHuEPO) has been used in cancer patients for the treatment of chemotherapy-induced anemia for two decades." (PMID 24165569, 2013). "The EPO expression level increased significantly with an increase in NHA grade in addition to the severity of the anemia in the patients with CHF complicated by anemia (P<0.05)." (PMID 24223667, 2013). "In contrast, erythropoiesis was provoked through treatments of erythropoietin, significantly ameliorating the anemia and reducing the mortality of LT-treated mice." (PMID 23977125, 2013).
anemia (continued). "Anemia is a common finding in hemodialysis patients with a prevalence of more than 80% and is frequently managed by erythropoietin (EPO) administration." (PMID 23547981, 2013). "Iron deficiency and tumor bleeding are common causes of anemia in ICC which are treated with either transfusion and/or erythropoietin prior to treatment." (PMID 24205226, 2013). "Most have focussed on how to reduce the need for blood transfusion by screening for anaemia and treating affected patients with erythropoietin stimulating agents, as before elective orthopaedic surgery." (PMID 23692862, 2013). "Administration of erythropoietin has been shown to correct anemia, suppress prolactin levels, improve general health status, induce sexual drive, stimulate regular menstruation, and, ultimately, promote fertility." (PMID 24198990, 2013). "In order to explore the correlation of Emp and erythroblastic island formation in bone marrow in patients with severe anemia treated with EPO." (PMID 23566571, 2013). "Further studies to evaluate the kinetics of the anti-EPO antibody and its neutralization of EPO activity will help deduce and understand further the development of anaemia in malaria." (PMID 23978045, 2013). "We aimed to investigate the hematopoietic function of bone marrow from 46 HSCT patients and 16 inpatients with severe anemia applied to the treatment of EPO by measuring Emp expression level." (PMID 23566571, 2013). "As for the anemia, mother received subcutaneous erythropoietin 8000 IU/week along with oral ferrous sulfate supplements 200 mg once daily." (PMID 24198990, 2013). "Persistent anemia and reticulocytopenia were observed and erythroid aplasia was established, even with erythropoietin use." (PMID 23343210, 2013). "In this review, we compared the effects of erythropoietin and anemia correction on kidney function (GFR) by investigating in various studies." (PMID 25340147, 2013). "Synthetic products of EPO, such as recombinant human EPO (rhEPO), have been successfully applied in clinical practice to treat anemia induced by diabetic nephropathy." (PMID 24137228, 2013). "Recently, also some investigators envisage administering the EPO therapy in chronic kidney disease (CKD) prior to anemia, which will benefit renal protective effectiveness of EPO in CKD." (PMID 24359941, 2013). "Medication review is needed in people with CKD and anaemia prior to considering erythropoietin or parenteral iron." (PMID 23351270, 2013). "Intravenous iron administration has been shown to reduce the need for EPO and to make anemia treatment more cost effective." (PMID 24373521, 2013). "During critical illness, the erythropoietic response to anemia is blunted by reduction in erythropoietin production and bone marrow suppression by various inflammatory cytokines." (PMID 23509619, 2013). "Anemia among patients with chronic kidney disease primarily occurs due to abnormal erythropoietin activity." (PMID 24086579, 2013). "The most common adverse events were dose-dependent anemia and thrombocytopenia, which were anticipated because thrombopoietin and erythropoietin signal through JAK2." (PMID 24283202, 2013). "Parvovirus B19 infection should be considered for the differential diagnosis of persistent anemia non responsive to erythropoietin, aplastic crisis and other opportunist infections in transplanted patients." (PMID 23343210, 2013). "Because EPO and EPOR are expressed in RCC (and in other cancers), the use of recombinant human EPO (rhEPO) to treat anaemia in cancer patients has been subject to considerable debate." (PMID 23305401, 2013). "In this study, 69 patients (31.8%) presented with CHF complicated by anemia, and their EPO levels increased significantly with the increased severity of CHF (P<0.05)." (PMID 24223667, 2013). "We demonstrated how the model can be used to support the planning of anaemia prophylaxis with EPO during chemotherapy." (PMID 23755260, 2013).
anemia (continued). "At 5 years post-transplant, only one patient with moderate anemia (hemoglobin: 7.2 g/dL) received erythropoietin therapy." (PMID 24237955, 2013). "Our data captures well-known controversies involving patents for primate embryonic stem cells involving the Wisconsin Alumni Research Foundation (WARF), breast cancer involving Myriad Genetics and erythropoietin involving Amgen for the treatment of anaemia." (PMID 24265714, 2013). "The use of EPO in therapy has been recommended to alleviate anaemia due to malarial infections and also in cerebral malaria management." (PMID 23978045, 2013). "The EPO level increased with an increase in the NYHA grade in addition to the severity of anemia, demonstrating significant differences among the various groups (P<0.05)." (PMID 24223667, 2013). "Grade 3 to 4 anemia, erythropoietin (EPO) use, transfusion or RBV dose reduction was recorded in 61% of patients." (PMID 24228933, 2013). "A clear temporal relationship between reduced renal function and the decline in erythropoietin production and development of anemia has been documented." (PMID 24086579, 2013). "In December 2010, the patient developed significant anemia, which was resistant to erythropoietin (1,119.0 mUI/mL) and, eventually, required blood transfusion." (PMID 23343210, 2013). "While early EPO administration is associated with improved survival due to amelioration of anemia, another study has indicated that in three mouse strains infected with the same pathogen, the anemia is insensitive to EPO treatment." (PMID 22094132, 2012). "Critically ill patients with anemia have been shown to have an inappropriately low erythropoietin response to their disease." (PMID 24066259, 2012). "Even though erythropoietin was widely used (85%), anemia was very common in Chinese dialysis patients." (PMID 22935444, 2012). "A third central EPOR signaling route involves a Jak2-plus-Stat5 axis which has been shown to be important for EPO-dependent erythropoiesis during anemia." (PMID 22808010, 2012). "Erythropoietin (EPO) and other erythropoiesis stimulating agents (ESAs) are the main stay for the treatment of anaemia of chronic kidney disease (CKD)." (PMID 23119160, 2012). "Recombinant human EPO (rhEPO) has been approved for the treatment of anemia resulting from chronic renal failure, cancer chemotherapy, AIDS, etc.." (PMID 22284751, 2012). "With regards to ligand concentration, EPO levels during anemia can increase several hundred-fold (and EPO at 3U/mL is required to support stress BFU-e development, for example)." (PMID 22808010, 2012). "Previous studies have reported that anemia is a poor prognostic factor for survival in patients with cancer and that erythropoietin (EPO) treatment can improve the survival rate and quality of life of patients with anemia receiving chemoradiotherapy." (PMID 22639817, 2012). "In an experiment where the recombinant EPO cDNA was expressed constitutively from a cytomegalovirus promoter, severe anemia (RCA) developed in some animals and polycythemia required repeated therapeutic phlebotomies to maintain nontoxic hematocrits." (PMID 23028782, 2012). "In summary, in adults, HIF-regulated renal EPO production provides the essential endocrine signal for the expansion of bone marrow RBC progenitors to compensate for anemia and hypoxia." (PMID 22094132, 2012). "Patients with inflammation, infections, or cancer have a reduced response to tissue hypoxia, and EPO plasma levels are always inappropriately lower for anemia." (PMID 23091709, 2012). "When EPO levels increase (e.g., due to anemia or anti-anemia therapy), cell surface-resident EPOR's rapidly (and transiently) convert to activated EPOR-72K species." (PMID 22253704, 2012). "Injection of exogenous recombinant human erythropoietin (rHuEPO) in these cats often results in the resolution of anemia, improvement in appetite, weight gain, energy level, alertness, playfulness, physical strength and attitude." (PMID 23028782, 2012).
anemia (continued). "Recently, recombinant EPO forms (epoetinalfa, epoetin-beta and the long-acting analogue darbepoetinalfa) have been widely used for treatment of anaemia in chronic kidney diseases." (PMID 22844537, 2012). "Early tubulointerstitial occurs which disease decreases EPO production and moreover inflammatory cytokines reduce EPO responsiveness leading to anaemia." (PMID 22845817, 2012). "The previous focus on EPO for anaemia correction still leaves unaddressed other determinants of chronic anaemia in diabetes." (PMID 22876293, 2012). "Profound anemia has also been reported in macaques treated with an AAV vector expressing EPO cDNA driven from a doxycycline-regulated promoter." (PMID 23028782, 2012). "Recombinant erythropoietin for the anaemia of patients with advanced Gastrointestinal Stromal Tumours (GIST) receiving imatinib : an active agent only in non progressive patients." (PMID 22950685, 2012). "Unfortunately, administration of recombinant human erythropoietin often only improves anemia temporarily due to antibody development." (PMID 23028782, 2012). "Hemodilution, absolute or functional iron deficiency, activation of the inflammatory cascade, and impaired erythropoietin production and activity are some pathophysiological mechanisms involved in anemia of the heart failure." (PMID 22536520, 2012). "Upon administration of EPO before the development of anemia, a poor clinical course has been observed." (PMID 22094132, 2012). "The primary cause of AOP is the impaired ability to increase serum erythropoietin (EPO) appropriately in the setting of anemia and decreased tissue availability of oxygen." (PMID 24575257, 2012). "Erythropoiesis-stimulating agents (ESAs), such as epoetin alfa (EPO) and darbepoetin, are used to treat anemia." (PMID 22577528, 2012). "The aim of this systematic review and meta-analysis was to examine the efficacy and harms of androgens for the treatment of anaemia of CKD compared to EPO from published randomized controlled trials." (PMID 23119160, 2012). "The only known agents available to treat pathological anemia are erythropoietin and its biologic derivatives." (PMID 22761764, 2012). "Prior to the advent of EPO in the 1980s and subsequently other ESAs, androgens such as nandrolone were used in the treatment of anaemia of CKD." (PMID 23119160, 2012). "Androgens which are relatively cheap were used in the treatment of anaemia in dialysis patients before the advent of EPO." (PMID 23119160, 2012). "Androgens which are relatively cheap were used in the treatment of anaemia in dialysis patients before the advent of Erythropoietin (EPO)." (PMID 23119160, 2012). "In fact, patients with chronic inflammatory diseases have been demonstrated to have decreased red cell survival, disorders of erythropoiesis, EPO levels low for the degree of anemia, and progressive EPO resistance of erythroid progenitors." (PMID 23091709, 2012). "In this systematic review and meta-analysis of randomized controlled trials, we found no clinically important or statistically significant difference between androgens (nandrolone) and EPO for the treatment of anaemia of CKD especially in men over 50 years." (PMID 23119160, 2012). "Mechanisms of cytokine related anaemia include reduction of renal EPO production, inhibition of the proliferation and differentiation of erythroid progenitor cells in the bone marrow, impaired iron absorption and reduced iron delivery." (PMID 22768256, 2012). "Decreased responsiveness of erythroid progenitor cells to erythropoietin as well as impaired erythropoietin production mediated by inflammatory cytokines has been reported to be involved in anaemia during inflammation." (PMID 22624872, 2012). "In chronic renal failure, the kidneys cease to make EPO, and commercially available preparations of recombinant human EPO (rHuEPO) are mainly used to treat anaemia secondary to chronic renal failure." (PMID 22462027, 2012).